IL6 (interleukin 6)
Diseases named in the same sentence as IL6 in open-access papers (continued):
Sharing a sentence is not in itself a finding about the gene and the disease.
COVID-19 (continued). "The results of our study indicated that serum levels of the molecules IL6, sIL1RII and GCSF are of high prognostic value for severe COVID-19 in the first week of hospitalization." (PMID 34829906, 2021). "Cytokines IL-1, IL-6, TNF, signal transducer and transcriptional activator 3 (STAT3), NF-κB, and lipopolysaccharides were the highest regulators of thrombotic markers in COVID-19 patients with severe-to-critical disease." (PMID 33995341, 2021). "Based on the 39 core common genes, immune system, cytokine/inflammatory response, signaling by interleukins, TNF-α signaling via NF-kB, IL-6/JAK/STAT3 signaling, TLR signaling, and AGE-RAGE signaling pathways, etc., are found as links between CVD and COVID-19." (PMID 34067609, 2021). "The group of COVID-19 patients with higher total and LDL-cholesterol levels was characterized by significantly lower CRP and IL-6 serum concentrations and significantly elevated PLT count and iron level." (PMID 34680053, 2021). "Of note, neutralizers of IL17, IL6, IL1, IFNA, IFNG, and TNF were predicted as antagonists of COVID-19 biology." (PMID 33782412, 2021). "Therefore, a reduced-innate antiviral defense coupled with exaggerated inflammatory IL-6 production might be responsible for SARS-CoV2 airway infection and dissemination as well as for the cytokine storm associated to worse progression in COVID-19 patients." (PMID 33216184, 2021). "Evaluation of cytokines at week 2 revealed that the levels of IL-4, IL-6, IL-10, and IFN-γ were higher, while the levels of IL-2 were lower in COVID-19 patients than that in HC." (PMID 33390771, 2021). "Serum levels of IL-6 and TNF-alpha were higher in COVID-19 children than in children with other infectious diseases, but those levels did not correlate with disease severity." (PMID 34578450, 2021). "It was found that those disorders that are characterized by persistently elevated levels of IL-6 exhibit diminished NK-cell function, including endometriosis, systemic juvenile idiopathic arthritis, heart failure, HIV, and severe COVID-19." (PMID 34439744, 2021). "In critical COVID-19 patients, a rise in serum IL10 levels occurs subsequently to elevated levels of innate inflammatory molecules IL-1β, IL-6, IL-8, and sTNFR1 during the course of the infection." (PMID 34829906, 2021). "One serum miRNA profiling study incorporated miR-146a-5p not only into COVID-19-related CSS, but also in the responsiveness of patients to CSS-countering treatment where IL-6 is the targeted cytokine." (PMID 34564316, 2021). "Coupled with the high IL-6, IL-10, and TNF levels, lymphopenia was observed in severe COVID-19 manifestations." (PMID 34912345, 2021). "Elevated serum levels of IL-6 and other pro-inflammatory cytokines, such as TNF-α and IFN-γ, are hallmarks of systemic inflammation of COVID-19, contributing to disease severity and adverse clinical outcomes." (PMID 34834033, 2021). "Another study observed elevated levels of IL-6 and TNF-α in children with COVID-19, as compared to those in controls; however, the increased levels of these cytokines lacked any correlation with disease severity." (PMID 34835108, 2021). "In the current study, we observed robust increases of proinflammatory cytokines/chemokines in sera and BALF, such as TNF-α, IL-1β, IL-6, KC, MCP-1, RANTES, and MIP-1α/β27,28 which correlate with those observed in severe COVID-19 and ARDS patients." (PMID 34952899, 2021). "The changes of systemic cytokines in AGMs following infection is consistent with COVID-19 patients: IFN-stimulated genes and IL-6 and IL-8 signaling upregulated." (PMID 34531831, 2021). "In these cohorts, race was also associated with inflammation, thromboinflammatory complications, body weight/BMI, and kidney dysfunction; indeed, IL-6, D-dimer, BUN, and creatinine levels were highest in individuals with COVID-19 of African descent." (PMID 34571942, 2021).
COVID-19 (continued). "In individuals with COVID-19, the enhanced serum level of the pleiotropic cytokine IFN-γ transcriptionally stimulates the production of IL-6 from the monocytes." (PMID 34102081, 2021). "For example, COVID-19 patients taking ACE/ARBs had lower levels of inflammatory markers, such as interleukin 6 (IL-6), C-reactive protein (CRP) and procalcitonin, than those not taking these drugs." (PMID 34090358, 2021). "Laboratory markers were characteristic for COVID-19, such as lymphopenia, elevated D-dimer, C-reactive protein (CRP), and interleukin 6 (IL-6)." (PMID 33732571, 2021). "Nevertheless, an intense increment of plasmatic levels of IL-6 and CCL5 (also known as RANTES), a ligand for CCR5, decreased CD8 + T cell levels, and SARS-CoV-2 plasma viremia in severe COVID-19 patients." (PMID 34753980, 2021). "A clinical study reported that the levels of IL-6, IL-10, and TNF-α were significantly increased in COVID-19." (PMID 34064553, 2021). "Pro-inflammatory cytokines, mainly IL-6, are involved in the pathogenesis of ALI, ARDS, and cytokine storm-induced multi-organ damage in COVID-19." (PMID 34568081, 2021). "Therefore, IL-6 and IL-10 can be used as predictors for rapid prognosis of COVID-19 patients with higher risk of disease deterioration, and the neutrophil-to-lymphocyte ratio and neutrophil-to-CD8+ T cell ratio have been identified as powerful predictors of severe COVID-19." (PMID 34818337, 2021). "In COVID-19, cytokine elevation has been described as a marker of worse progress (higher ARDS and death rates), with involvement serum levels of both IL-1 and IL-6." (PMID 33467585, 2021). "Significantly higher levels of galectin-3, galectin-9, IL-1β, IL-1Ra, IL-10, IFN-α2, IL-6, IL-18, and TNF-α were observed in severe COVID-19 and active AOSD patients compared with HC (all p<0.001)." (PMID 34367188, 2021). "Elevated serum levels of inflammatory cytokines, including interleukin (IL)-2, IL-4, IL-6, IL-7, IL-10, tumor necrosis factor (TNF), and interferon (IFN)-γ, have been reported in severe COVID-19 patients." (PMID 34959657, 2021). "In our model, VPA reduces the expression of the pro-inflammatory cytokines TNF-α and IL-6 even after SARS-CoV-2 infection, making VPA a promising candidate for the treatment of COVID-19 patients." (PMID 34635175, 2021). "The proinflammatory cytokines TNF-α, IL-1β, IL-8, IL-6, and IL12-B (P < 0.05) were increased in patients who had contracted COVID-19." (PMID 33819170, 2021). "Immune phenotyping based on the LDH, IL-6, D-dimer, and NLR is a well-established marker in predicting disease severity and ICU-mortality outcomes in patients with COVID-19." (PMID 35071229, 2021). "Clinical studies have indicated that the levels of IFN-γ, IL-6, TNF-α, IL-2, MCP-1, and other pro-inflammatory cytokines are significantly increased in severe or critical COVID-19 patients." (PMID 33995078, 2021). "Ca2+ in COVID-19 patients was significantly negatively correlated with PCT, calcitonin, D-dimer, PFDP, ESR, CRP and IL-6." (PMID 34222271, 2021). "Levels of IL-6, IL-10, IL-15, IFN-γ, TNF-α, CCL2, CCL3, CCL4, CCL26, CXCL9 and CXCL10 were significantly elevated both in COVID-19 critical clinical condition and in MAS patients as compared to healthy controls." (PMID 34226537, 2021). "Many proinflammation cytokines, including IL-2, IL-6, IL-7, IL-10, granulocyte colony stimulating factor (GCSF) and TNF-α, were significantly increased in the periphery of severe COVID-19 patients." (PMID 33912590, 2021). "Elevated levels of infection-related biomarkers (ESR, IL2R, IL6, IP10, PCT, SF, CRP, TNFα) were detected in many patients with severe COVID-19." (PMID 33542448, 2021). "Many of these cytokines, including IL-6, IL-18, IL-33, MCP-1, and MIP-1α, were elevated in the COVID-19 ICU and/or in-hospital mortality groups in our study." (PMID 34960684, 2021).
COVID-19 (continued). "The levels of IL-6, IL-8, and MIP-1β significantly decline at month 1 in patients with severe COVID-19, showing during the subsequent follow up levels similar to those found in patients with mild/moderate disease." (PMID 34835384, 2021). "In multivariate analysis, elevated levels of troponin [OR 1.54; (95% CI 1.22–1.96), p < 0.001)], IL-6 [OR 1.69 (95% CI 1.26–2.27), p < 0.013)], and CRP [OR 1.32; (95% CI 1.1–1.58), p < 0.003)] were predictors of mortality in patients with COVID-19." (PMID 33211155, 2021). "Given that dexamethasone appears to reduce mortality among only severe cases of COVID-19, we finally asked how NR3C1 and IL-6 co-expression varies between mild and severe disease." (PMID 33723251, 2021). "Importantly, IL-6 is not only an important biomarker and possible target for cardiovascular morbidity and mortality, but may also serve as a therapeutic target in patients with COVID-19." (PMID 33211155, 2021). "As early as February of 2020, the anti-IL-6 receptor (IL-6R) blocking antibody tocilizumab was assessed for therapeutic efficacy in a randomised control trial in China to counter the putative COVID-19-induced CSS, where IL-6 is thought to play a key role." (PMID 34564316, 2021). "In this article, we summarize reports on the plasma levels of cytokines IL-6, TNF-α and IL-28B and the biomarkers of cardiovascular disease, cTnT, NT-proBNP, PAPP-A and IMA, in a retrospective study of 84 patients with COVID-19." (PMID 34884175, 2021). "The present study on critically ill COVID-19 patients with moderate to severe ARDS showed a correlation of serum albumin, IL-6, and D-dimer all together at admission to ICU, accompanied by chest CT severity score, as independent predictors of mortality." (PMID 33968298, 2021). "In the severe stage of COVID-19, shock, and respiratory and systemic organ failure may manifest secondary to a surge of proinflammatory cytokines (cytokine storm) which include IL-6, IL-1β, IL-2, granulocyte colony stimulating factor, macrophage inflammatory protein 1-α and tumor necrosis factor." (PMID 34276355, 2021). "In the acute COVID-19 group, HA positively correlated with FIB-4, AST, ALT, LDH, IL-6, and ferritin and negatively with blood oxygen saturation." (PMID 34635073, 2021). "IL6, CXCL8, EGFR, FOS, PIK3R1, and NFKB1 were identified as common targets from the common pathways between cancers and COVID-19 (signaling by interleukins, TLR signaling, TNF-α signaling via NF-kB)." (PMID 34067609, 2021). "Immune dysfunction in COVID-19 patients has been attributed to pro-inflammatory cytokines including Tumor necrosis factor-α (TNF-α) and interleukin-6 (IL-6)." (PMID 35127733, 2021). "GCSF, IL-1RA, IL-6, IL-8, IL-10, IL-12 (p40), MCP-1, M-CSF, and TNF-α were correlated with SOFA scores in COVID-19 patients and controls, with increased cytokine expression positively correlating with higher SOFA scores." (PMID 34131192, 2021). "In the acute COVID-19 group, the medians of LDH, CRP, ferritin, IL-6, and ESR at admission to the hospital were higher than the upper limit of a reference interval." (PMID 34635073, 2021). "Considering all COVID-19 subjects, we observed a positive correlation between sCD163 and LDH plasmatic levels (ρ=0.310, p=0.002) and between sCD163 and IL-6 plasmatic levels (ρ=0.472, p=0.006)." (PMID 33777012, 2021). "Elevated concentrations of cytokines including IL-6, as well as increased CRP and D-dimer concentrations, are common in severe COVID-19 patients, and the uncontrolled inflammatory response has been deemed responsible for the most severe forms of COVID-19." (PMID 34822379, 2021). "Our results showed that with the severity of COVID-19 worsens, the count of WBC, NEUT, IL-6, and IL-10 increased significantly, while LYM levels decreased." (PMID 33557779, 2021).
COVID-19 (continued). "In this study, levels of serum proinflammatory cytokines increased in most patients with COVID-19, and the level of most cytokines (e.g., TNF-α, IL-6, and IL-8) were greatly higher in critical patients than in severe cases." (PMID 34725309, 2021). "IL-6 is a key inflammatory cytokine in SARS-CoV-2 infection, and its levels in COVID-19 patients are higher than those usually seen in severe bacterial sepsis." (PMID 34566657, 2021). "Longitudinal studies have demonstrated gradual declines of serum concentration of inflammatory biomarkers including IL-6, IL-8, tumor necrosis factor-α, and high-sensitivity C-reactive protein (hs-CRP) at the late stage of illness in COVID-19 survivors." (PMID 34912863, 2021). "Our data confirmed that IL-6, CRP and ferritin levels are higher in severe COVID-19 cases and in patients with fatal outcome and showed negative correlations between these parameters and 25(OH)D." (PMID 34578898, 2021). "The use of IFN-α2-β in combination with Arbidol significantly reduced the virus persistence in the upper respiratory tract and shortened the presence of the inflammatory markers IL-6 and CRP in adults hospitalized with COVID-19 at the same time." (PMID 34603758, 2021). "It should be noted that the cytokine profile similar to MAS/sHLH has also been observed in COVID-19 patients, especially the increase of IL1β, IL2, IL6, IL17, IL8, TNF and CCL2." (PMID 34912345, 2021). "The hyper-inflammatory state, where IL-6 and C-reactive protein (CRP) levels are raised, has been shown to predict severity of disease in some COVID-19 patients." (PMID 34834033, 2021). "Therefore, we speculate that IL-2R, IL-6 and CRP are associated with the severity of COVID-19." (PMID 33542448, 2021). "These values of IL-6 might be used for classification of COVID-19 patients according to their prospective respiratory condition in the short term, for example, with a higher value of IL-6 than 91.5 for the respiratory deterioration group and a lower value of IL-6 than 43.9 for the stable group." (PMID 34441262, 2021). "Longitudinal analysis showed IL-6 (hazard ratio [HR] 6.81, 95% confidence interval [CI] 1.6-28.7) and MCP-1 (HR 4.61, 95%CI 1.1-19.1) to be related to mortality in hospitalized COVID-19 patients." (PMID 34539631, 2021). "In most cases of COVID-19, increased levels of pro-inflammatory cytokines such as IL-2, TNF-α, IL-1β, IFN-γ and IL-6 and chemokines such as monocyte chemo-attractant protein-1 and macrophage inflammatory protein-1α were observed." (PMID 34649460, 2021). "Many inflammatory cytokines (Interferon-alpha (IFN-α), interleukin-1beta (IL-1β), interleukin 6 (IL6), interleukin 12 (IL-12), tumor necrosis factor-alpha (TNF-α), and transforming growth factor-beta (TGFβ) and chemokines were detected in COVID-19 patients." (PMID 34908920, 2021). "The levels of serum proinflammatory cytokines and chemokines were also found to increase in patients with COVID-19, including tumor necrosis factor α (TNF-α), interferon-γ (IFN-γ)-induced protein 10 (IP-10), interleukin-6 (IL-6), IL-8, and IL-10." (PMID 33937333, 2021). "Increased concentrations of inflammatory cytokines (IL-6, granulocyte-macrophage colony stimulating factor (GM-CSF) and tumor necrosis factor-a (TNF-a) are reported in persons with COVID-19." (PMID 34002026, 2021). "Therefore, we cannot discard that the hypozincemia observed in COVID-19 patients might be caused and worsened by a negative IL-6 production loop." (PMID 33572045, 2021). "As inflammatory macrophages are suspected to be the main producer of inflammatory cytokines such as IL-6 and IL-1β, we looked for possible enrichment of inflammatory macrophages in the BAL from patients who died owing to COVID-19." (PMID 33674591, 2021). "Studies have shown that the levels of various cytokines such as IL-2R, IL-6, IL-10, IL-2, IL-7, GCSF and TNF-α are significantly higher in patients with severe COVID-19 compared with patients who have a mild disease." (PMID 34490065, 2021).
COVID-19 (continued). "Given the heterogeneous preliminary results so far in trials applying IL-6 blockade in more severe cases of COVID-19, the results of the present study may suggest to elucidate the specific role of IL-6 blockade in uncomplicated COVID-19 patients with cardiovascular comorbidities." (PMID 33211155, 2021). "Severe COVID-19 cases exhibit high levels of IFN-γ and IL6 and a skewing towards Th17 cells; moreover, IL-17 levels correlate with clinical severity, suggesting the opportunity of therapeutically inhibiting the Th17 axis." (PMID 34646278, 2021). "Multivariate logistic regression analysis was performed to ascertain the effects of age, IL-6, and TNF-α levels on the likelihood that participants had COVID-19." (PMID 34578450, 2021). "Moreover, acute clinical deterioration in moderate COVID-19 patients requiring inpatient care may be the result of increased inflammation due to elevated cytokine levels, such as type I IFNs and IL-6, all of which transmit their signals through the JAK-STAT pathway." (PMID 34959657, 2021). "Increasing evidence suggests that cytokines such as IL-6, IL-1β receptor, IFN-γ, and TNF-α play a key role in the pathogenesis of COVID-19." (PMID 33995341, 2021). "Kaplan-Meier survival curves showed that higher IL-2R, IL-6, IL-8, IL-10, and TNF-α levels were significantly correlated with reduced survival time in COVID-19 (all P < 0.001)." (PMID 33542929, 2021). "We observed activation of NF-κB signaling and activation of target genes, TNF-α, IL-6, and CCL5, following exposure of hepatocytes to exosomes isolated from plasma of COVID-19 patients." (PMID 33804769, 2021). "IL-6 has been shown to be highly expressed in respiratory infections, including SARS-CoV-2/COVID-19 patients and other respiratory infections." (PMID 34943813, 2021). "Higher levels of IgA, IgM, and IgG and the specific cytokines IL-6, IL-8, and MIP-1β during acute infection were observed in those patients with a severe COVID-19 outcome." (PMID 34835384, 2021). "It is noteworthy that IL-6 and TNF-α are significantly elevated in patients with severe COVID-19, and that LIF is an IL-6 cytokine that can activate the JAK/STAT and MAP kinase pathways." (PMID 34395311, 2021). "We also found that the levels of pro-inflammatory cytokines and infection-related biomarkers were higher in severe COVID-19 patients with cancer, including procalcitonin, CRP and IL-6." (PMID 34353293, 2021). "We believe that the biomarkers used in the COVID-IRS scores (respiratory rate, SaO2/FiO2 ratio, LDH, and either IL-6 or NLR), accurately represent relevant aspects of the clinical phenomena seen in severe COVID-19." (PMID 33819261, 2021). "Acute serum IL-6 and CRP levels were then compared to those with suspected COVID-19 (SCOVID) and age and sex matched patients with SAB and patients hospitalized for any non-infectious condition (NIC)." (PMID 33815405, 2021). "Clinical evidence has revealed interleukin (IL)-6, a major chemokine in CRS, to be a critical biomarker and predictor for severe COVID-19." (PMID 33520118, 2021). "An increase of HPG, CXCL9, CXCL10, IL-6, MCP-3, TNF and EN-RAGE has also been experimentally detected in patients with severe COVID-19." (PMID 34335580, 2021). "A main factor contributing to COVID-19 severity is believed to be development of the cytokine storm, the uncontrolled release of various inflammatory markers (such as CRP, IL-6, ferritin, tumor necrosis factor α or neutrophil-to-lymphocyte ratio (NLR))." (PMID 34578898, 2021). "Inflammatory cytokines IL1β, IL6, IL8, and TNFα increased in the plasma of moderate and severe COVID-19 patients." (PMID 33767630, 2021). "In 2019 coronavirus disease (COVID-19), severe acute respiratory syndrome (SARS) and Middle East respiratory syndrome (MERS), the abnormal increase in IL-6 is related to the severity of the disease." (PMID 34925324, 2021).